EGFR (epidermal growth factor receptor)
Diseases named in the same sentence as EGFR in open-access papers (continued):
Sharing a sentence is not in itself a finding about the gene and the disease.
malignant glioma (94 papers, 2004 to 2025). A grade III or grade IV glioma arising from the central nervous system. "The classical subtype accounts for approximately 25% of malignant gliomas, and is characteristically marked by Epidermal Growth Factor Receptor (EGFR) amplification/mutation." (PMID 35477752, 2022). "NG2/CSPG4 immunoreactivity was significantly associated with EGFR gene amplification (p = 0.0005, Fisher’s exact test) in malignant gliomas and with 1p/19q-codeletion in oligodendroglial tumors (p = 0.0297, Fisher’s exact test)." (PMID 32599896, 2020). "Among them, alterations of EGFR including gene amplification and activation mutations are observed in 40–57 % of malignant gliomas." (PMID 26861698, 2016). "The most common genetic aberration associated with malignant glioma is amplification of EGFR, with a frequency of about 50%." (PMID 26328271, 2015). "EGFR is one of the key oncogenes subjected to targeted therapy for several cancers, as it is known to be amplified and/or mutated in up to 40% of malignant gliomas." (PMID 25594013, 2014). "Dysregulation of EGFR via overexpression, amplification, and mutation affects the majority of malignant gliomas." (PMID 22918789, 2012). "In particular, the links between ASPM and key molecular alterations of malignant gliomas, such as EGFR amplification or mutation (EGFRvIII) (an almost constant feature in gliomaspheres - 80% in our experience), remain to be investigated." (PMID 20142996, 2010). "Approximately 50% of malignant gliomas show a mutation in the EGFR." (PMID 38927583, 2024). "It would be very valuable to know whether the cooperative relationship between NTSR1 and EGFR system exists in malignant glioma, and what its underlying molecular mechanism is." (PMID 25644759, 2015). "For example, attempts to target mutated, upregulated epidermal growth factor receptor (EGFR), the most common genetic aberration associated with malignant glioma and an upstream component of the MAPK pathway, has been largely unsuccessful due to both inherent and acquired resistance." (PMID 26525348, 2015). "High EGFR expression and mutations in EGFR are prevalent in malignant glioma." (PMID 25644759, 2015). "The EGFR gene is frequently amplified and rearranged in malignant gliomas with an expression of oncogenic deletion mutants." (PMID 39087020, 2024). "RRAD promotes malignant glioma progression via endosome-mediated epidermal growth factor receptor (EGFR)/STAT3 signaling." (PMID 36979412, 2023). "EGFR-targeted therapy has attracted much attention due to frequent alterations in malignant gliomas." (PMID 36900355, 2023). "ERK cascade signaling is essential to the production of inflammatory cytokines, and this signaling pathway is hyperactive in malignant gliomas due to overexpression of EGFR and PDGFR." (PMID 35327982, 2022). "The most frequent genetic aberration associated with malignant glioma is an amplification of the EGFR, also referred to as ERBB1 or human epidermal receptor 1 (HER1), and the expression of the EGFR variant III (EGFRvIII)." (PMID 34209513, 2021). "For instance, ShcD can bind and promote ligand-independent activation of EGFR, and its expression parallels EGFR hyperphosphorylation in malignant gliomas." (PMID 33673213, 2021). "Although EGFR inhibitors have promising potential, clinical application remains challenging with monotherapy or combination therapy in combating malignant glioma." (PMID 33920356, 2021). "Another promising marker for malignant glioma is the amplification of the epidermal growth factor receptor (EGFR) expression with a frequency of about 50%." (PMID 33916177, 2021). "Cinobufagin is a potential therapeutic agent for treating malignant glioma and other human cancers expressing EGFR." (PMID 34925034, 2021). "The mAb806 antibody has been tested in clinical trials for EGFR-overexpressing tumors, and showed specific binding to tumor tissue, including malignant glioma, with only mild gastrointestinal and dermatologic side effects." (PMID 31903167, 2019).
malignant glioma (continued). "The same effect of ZR30 on blocking EGFR signaling was also seen in malignant glioma cell line T98G." (PMID 29290950, 2017). "In general, the resistance mechanisms against EGFR inhibitors are found within the complexities of malignant glioma’s signaling network and many of the mechanisms regulating tumor growth remain to be explained." (PMID 26525348, 2015). "EGFR is a prominent target in cancer therapy—overexpression of EGFR was first identified in malignant gliomas in 1987." (PMID 26689952, 2015). "Another receptor that is also a promising marker for malignant gliomas is the epidermal growth factor receptor (EGFR)." (PMID 28347118, 2015). "Combining MK2206 with gefitinib has also been shown to be successful in EGFR expressing malignant glioma cells, where combined therapy resulted in a synergistic increase in apoptosis and autophagy in vitro, and increased anti-tumor activity in vivo." (PMID 24946858, 2014). "The oncogenic effect of EGFR overexpression in tumors has been well documented; it is commonly observed in malignant gliomas and, in large part, results from EGFR gene amplifications." (PMID 25594013, 2014). "Preclinical data suggest that over-expression of EGFR confers radiation resistance on malignant glioma and that blocking EGFR restores radiosensitivity." (PMID 24418474, 2014). "Malignant gliomas, particularly GBM, frequently display amplification of EGFR, specific activating mutations in EGFR and, to a lesser extent PDGFR amplification." (PMID 23998913, 2013). "Malignant gliomas frequently overexpress the EGFR, and binding of the EGFR inhibits tumor growth and induces apoptosis in tumor cells." (PMID 23762610, 2013). "It has been reported that increased mitogenic signaling and angiogenesis, frequently facilitated by somatic activation of EGF receptor (EGFR; ErbB1) and/or loss of PTEN, and VEGF overexpression, respectively, drive malignant glioma growth." (PMID 24294521, 2013). "In a previous study, a polymorphism in the 5′-untranslated region of the epidermal growth factor (EGF) gene, a natural ligand of the EGFR, was identified to play an important role in the pathogenesis of malignant gliomas." (PMID 22662167, 2012). "A phase II study of bevacizumab plus erlotinib, an epidermal growth factor receptor (EGFR) tyrosine kinase inhibitor, was performed for patients with recurrent malignant gliomas." (PMID 21804824, 2012). "Targeting molecular aberrant pathways have been one option to enhance treatments against malignant gliomas, including inhibition of the epidermal growth factor receptor (EGFR)." (PMID 22918789, 2012). "Disregulation of HER1/EGFR is related to malignant transformation and tumor growth in various human cancers, including malignant glioma." (PMID 20657384, 2010). "The constitutive activation of STAT3 coexists with EGFR expression in 27.2% of primary high-grade/malignant gliomas." (PMID 20113523, 2010). "In a clinical study of EGFR tyrosine kinase inhibitor (erlotinib) on malignant gliomas patients, AKT activation status was found to determine the response of the tissue to the inhibitor, suggesting that p-AKT had mediated EGFR signaling in the patients." (PMID 19662227, 2007). "Optimization of this compound might warrant a new drug for the treatment of malignant glioma and other human cancers expressing EGFR." (PMID 34925034, 2021). "In this study, iron oxide nanoparticles (IONPs) were conjugated to an antibody specific to the epidermal growth factor receptor (EGFR) deletion mutant (EGFRvIII), which is present in malignant gliomas and contributes to tumorigenicity and resistance to chemotherapy." (PMID 33391494, 2021). "Cinobufagin might be a therapeutic compound for the treatment of malignant glioma and other human cancers expressing EGFR." (PMID 34925034, 2021).
malignant glioma (continued). "High levels of LRIG3 is associated with the downregulation of EGFR and MET signaling in malignant gliomas, supporting the idea that LRIG3 may be a novel target for anti-angiogenic therapy." (PMID 33718179, 2021). "Additionally, despite the encouraging apoptotic and autophagic consequences in cell studies, EGFR inhibitors, including gefitinib, have only marginal benefits in patients with recurrent malignant glioma." (PMID 33920356, 2021). "EGFR alterations are commonly observed in malignant gliomas (MG)." (PMID 35601813, 2021). "EGFR gene amplification occurred in 19/45 (42.2%) malignant gliomas." (PMID 32599896, 2020). "Because the NTS/NTSR1-induced transactivation of the EGFR signaling pathway may complicate EGFR-targeted therapies in malignant glioma." (PMID 25644759, 2015). "EGFR expression and signaling is known to be important to the pathobiology of malignant glioma." (PMID 26023796, 2015). "A promising antigen for peptide vaccination is epidermal growth factor receptor (EGFR), a transmembrane tyrosine kinase receptor that is rearranged and overexpressed in nearly half of malignant gliomas, resulting in structural rearrangements and enhanced oncogenicity." (PMID 25268164, 2014). "Other EGFR mAbs, trastuzumab (Herceptin) and panitumumab (Vertibix), have been applied to numerous patients with breast and colon cancers, respectively, but little study of malignant glioma has been reported." (PMID 23762610, 2013). "EGFR is an important mediator responsible for the invasiveness of malignant gliomas." (PMID 23076445, 2013). "Our data revealed that EFEMP1 is a favorable prognostic factor for GBM, has a tumor-suppressive effect in malignant glioma cells, and acts in the extracellular compartment via independent blocking of EGFR and AKT signaling pathways while also repressing VEGFA-induced angiogenesis." (PMID 21955618, 2011). "According to the results, 11C-PD153035 PET/CT was a promising tool for EGFR-targeted molecular imaging of GBM, which could translate into clinical applications to select patients suitable for EGFR-targeted therapies and to assess the early response of malignant gliomas to such therapies." (PMID 39355049, 2023). "Other results derived from the analysis of EGFR/EGFRvIII and PTEN in recurrent malignant gliomas from patients who received EGFR kinase inhibitors revealed that co-expression of EGFRvIII and PTEN was associated with responsiveness." (PMID 35158868, 2022). "We show that second-generation EGFR806-CAR T cells with a short spacer can eradicate malignant glioma in a xenograft mouse model via intracranial delivery, and that CAR T cell activation is specific to tumor-expressed EGFR." (PMID 31903167, 2019). "To validate EGFR as a suitable target for CAR based immunotherapy, we confirmed expression of EGFR on 35 separate malignant glioma samples via tumor tissue microarray." (PMID 31903167, 2019). "Because sustaining proliferative signaling is another hallmark of cancer, we explored the receptor tyrosine kinase (RTK) signal pathways by analyzing genes known to promote the EGFR, FGFR, and PDGFR signaling commonly seen in malignant gliomas." (PMID 27852048, 2017). "Further evidence for a regulatory link between EGFR and TERT was reported recently in malignant glioma, where 92% of cases harboring EGFR amplification were accompanied by a mutation in the TERT promoter." (PMID 24152305, 2013).
malignant glioma (continued). "Epidermal growth factor receptor and its main ligands EGF and transforming growth factor alpha (TGFα) are commonly overexpressed in malignant glioma." (PMID 15305185, 2004). "Epidermal growth factor receptor overexpression and activation of downstream signaling pathways, including RASYRAFYMAPK and PI3K/AKT, is considered to play a critical role in developing and progressing malignant gliomas." (PMID 39355049, 2023). "Treatment of cells with antisense miR-21 was shown to decrease the expression of epidermal growth factor receptor (EGFR) and activate AKT, cyclin D, and BCL-2, which suggests that miR-21 may be a novel therapeutic target for malignant gliomas." (PMID 35173580, 2022). "Two other clinical studies showed that treatment of recurrent malignant gliomas with erlotinib, a receptor tyrosine kinase inhibitor of EGFR, had no benefits compared with control regimens." (PMID 36135196, 2022). "Although it remains to be directly shown that the Tn antigen of EGFR is responsible for the change in EGFR function, it has been suggested that GALNT2 may be a marker for malignant gliomas." (PMID 34069424, 2021). "Clinical findings reveal that only 10–20% of malignant glioma patients benefit from the gefitinib and the coexpression of the EGFRvIII oncogene, and the PTEN tumor suppressor protein in patients favors a clinical response to EGFR inhibitor therapy." (PMID 33920356, 2021). "In contrast, in malignant gliomas, NG2 is symmetrically expressed in both daughter cells resulting in active expression of other growth factor receptors including epidermal growth factor receptor (EGFR)." (PMID 25987129, 2015). "Furthermore, targeting gene fusions involving EGFR, FGFR, MET or NTRK may soon represent a promising therapeutic option for several types of cancer including malignant glioma." (PMID 35372034, 2022). "This possibly suggests that apart from catalyzing dephosphorylation of EGFR and β-catenin, PTPRK also regulates their protein expression in malignant glioma by interacting directly with transcription or by negative feedback-loop after dephosphorylation of EGFR and β-catenin." (PMID 23696788, 2013).
interstitial lung disease (91 papers, 2010 to 2026). A diverse group of lung diseases that affect the lung parenchyma. "Fatal toxic effects associated with EGFR-TKIs were overall rare (1.33%), with interstitial lung disease (ILD) being the most common cause of death." (PMID 41585870, 2025). "The specific mechanism underlying the development of EGFR-TKI-induced Interstitial Lung Disease (ILD) remains elusive." (PMID 38895622, 2024). "TKI of ERBB1/EGFR cause treatment-emergent side effects some of can be associated with potentially fatal serious toxicities such as lung injury/interstitial lung disease, especially in patients with preexisting pulmonary disease." (PMID 36311273, 2022). "Especially, previous studies reported that the administration of EGFR tyrosine kinase inhibitors (TKIs) increased the risk of interstitial lung disease after treatment with ICI." (PMID 35901098, 2022). "EGFR TKI combination with immunotherapy was found to be associated with a high incidence of interstitial lung disease." (PMID 31722672, 2019). "Subsequent next-generation sequencing analysis revealed both ROS1 rearrangement and an EGFR exon 19 deletion mutation in lung biopsy specimens, which were histologically confirmed to be interstitial lung disease." (PMID 30029601, 2018). "The POLARSTAR study, a phase IV surveillance study on erlotinib in patients unselected for EGFR mutation status in second-line and beyond, focused on interstitial lung disease (ILD) and PFS." (PMID 30021993, 2018). "Takada etal. showed Fra-1 was involved in lung interstitial disease associated with EGFR-TKI treatment in lung cells." (PMID 23592411, 2013). "These include underlying lung diseases (interstitial lung diseases, chronic obstructive pulmonary disease), performance status, prior thoracic radiotherapy, and the treatment combination of epidermal growth factor receptor (EGFR)-tyrosine kinase inhibitors with ICIs." (PMID 34680601, 2021). "In addition, those patients who were EGFR wild-type had some clinical risk factors of interstitial lung disease with EGFR-TKI." (PMID 31049758, 2019). "However, EGFR-TKI increases the risk of developing life-threatening interstitial lung diseases (ILDs)." (PMID 22191026, 2011). "EGFR-TKI-associated interstitial lung disease (ILD) incidence across pivotal trials and real-world studies." (PMID 41585870, 2025). "Although EGFR-TKIs have proven efficacy, their associated adverse reactions require careful attention, particularly interstitial lung disease (ILD)." (PMID 40949116, 2025). "A number of studies have indicated that patients with EGFR-mutated NSCLC undergoing osimertinib treatment may be susceptible to developing interstitial lung disease (ILD), which can potentially lead to treatment interruptions, medication adjustments, and even jeopardise the patient’s life safety." (PMID 38895622, 2024). "A phase 1b multicenter trial showed that the combination of Durvalumab and Osimertinib in the treatment of EGFR mutation-positive NSCLC patients can increase the incidence of interstitial lung disease (ILD)-related adverse events (AE) (35%)." (PMID 37799725, 2023). "On the other hand, treatment with EGFR-TKIs is associated with serious side effects, such as life-threatening drug-induced interstitial lung disease (ILD), particularly in Japanese populations." (PMID 21791074, 2011). "Our results identified significant signals for interstitial lung disease and acute respiratory distress syndrome across all EGFR-TKIs." (PMID 40949116, 2025). "Herein, we describe a case of patient co-harboring EGFR Ex19del mutation and MET de novo amplification who presented targeted (almonertinib)-induced interstitial lung disease (ILD)." (PMID 40034596, 2025). "Regarding safety, commonly reported AEs of second- and third-generation EGFR-TKIs included rash, dry skin, diarrhea, paronychia, and interstitial lung disease." (PMID 40349136, 2025).